ANXA5 (annexin A5)
Diseases named in the same sentence as ANXA5 in open-access papers (continued):
Sharing a sentence is not in itself a finding about the gene and the disease.
thrombosis (14 papers, 2014 to 2025). "These autoantibodies are described to neutralize the anticoagulant effect of ANXA5 derived from endothelium and can thus increase the risk of thrombosis in APS." (PMID 34859078, 2021). "HCQ could also prevent β2-glycoprotein I complex from binding to phospholipid bilayers and cells and protect the annexin A5 anticoagulant shield from being destroyed by antiphospholipid antibodies, which was considered to decrease the risk of thrombosis in APS and SLE." (PMID 36238309, 2022). "Anti-Annexin A5 antibodies have been proposed to be associated with the clinical features of APS, including thrombosis and recurrent miscarriages." (PMID 33182499, 2020). "Indeed, the anti-β2-GPI are able to bind to the monolayers of endothelial or trophoblast cells and, by destroying the anticoagulant shield of Annexin A5, to induce a procoagulant state in the placenta leading to thrombosis and heart attack." (PMID 33182499, 2020). "Inflammation; Pathophysiology; Hematological System; Immunology; Laboratory Medicine; Clinical Research; Portal vein thrombosis; PhosphatidylSerine bearing microparticles (PS + MPs) levels; plasma AnxA5 level; plasma Annexin A5/PS + MP ratio; Portal flow velocity." (PMID 32904199, 2020). "With regards to circulating ANXA5, studies have also reported a great abundance of ANXA5 in advanced atheroma; nevertheless, while ANXA5 level is known for its antithrombotic role in the formation of arterial thrombosis, it might also contribute to plaque volume increase during disease progression." (PMID 36009365, 2022). "Although AnxA5 deficiency was initially not considered to interfere with embryonal development, in later studies reduced litter size, increased foetal loss and placental thrombosis of maternally homozygous progeny were reported." (PMID 33810523, 2021). "Similarly, HCQ has been shown to reduce the extent of thrombosis in an animal model of injury-induced thrombosis in APS, reverse aPL-induced platelet activation and to protect the EC annexin A5 anticoagulant shield from disruption by aPL54." (PMID 28883515, 2017).
Cirrhosis (13 papers, 2017 to 2025). A chronic disorder of the liver in which liver tissue becomes scarred and is partially replaced by regenerative nodules and fibrotic tissue resulting in loss of liver function. "Similarly, Serag and Elsayed have found that serum ANXA5 has a prognostic value for HCC in hepatitis C virus-associated cirrhosis patients." (PMID 37117324, 2023). "Using the ROC curve in Cirrhosis with HCC group, annexin A5/MP ratio had the largest AUC, 0.921, followed by PS + MPs level, 0.854, Portal flow velocity, 0.828, Plasma Annexin A5 level, 0.566." (PMID 32904199, 2020). "Using the ROC curve in Cirrhosis without HCC group, annexin A5/MP ratio had the largest AUC, 0.951, followed by PS + MPs level, 0.917, Portal flow velocity, 0.854, Plasma Annexin A5 level, 0.571." (PMID 32904199, 2020).
endometrial cancer (12 papers, 2014 to 2024). Primary or metastatic malignant neoplasm involving the endometrium (mucous membrane that lines the endometrial cavity). "ANXA5, serving as a marker for macrophage subsets, could predict immune therapy responses in endometrial cancer." (PMID 38287304, 2024). "Upregulation of annexin A5 in endometrial cancers has not been reported so far." (PMID 35454982, 2022).
Obesity (12 papers, 2007 to 2025). Accumulation of substantial excess body fat. "As it is stated, higher abundance of ANXA5 in proteome of individuals with obesity may be associated with the development of obesity and could mediate in some coagulation disorders related to this condition." (PMID 38703299, 2024). "ANXA5 protein was induced in adipocytes during aging and one study demonstrated an association of ANXA5 polymorphisms with obesity in a Korean patient cohort, which may suggest a function of ANXA5 on the fat deposition, storage or mobilization." (PMID 38703299, 2024). "Other module genes related to lipid metabolism and obesity include Anxa5 (annexin A5), Ccna2 (cyclin A2), Ces5 (carboxylesterase 5), Cyp2c38 (cytochrome P450, family 2, subfamily c, polypeptide 38), Setd8 (SET domain containing 8), and Slc16a11 (monocarboxylic acid transporters, member 11)." (PMID 21179437, 2010).
systemic lupus erythematosus (12 papers, 2009 to 2026). An autoimmune multi-organ disease typically associated with vasculopathy and autoantibody production. "In a wider context, it is noteworthy that in systemic lupus erythematosus increased concentration of anti-ANXA5 antibodies was accompanied by an increased concentration of ANXA5 in the plasma." (PMID 34859078, 2021). "Among systemic lupus erythematosus (SLE) patients with APS-related clinical manifestations, IgG AnxA5-Abs prevalence was 31.7% versus 16.3% in SLE controls without clinical APS manifestations." (PMID 42125052, 2026).
thyroid cancer (11 papers, 2014 to 2024). "Annexin A5 is generally upregulated in a variety of cancers, but in the case of thyroid carcinoma, it has been negatively correlated with malignancy, with lower expression in FTC than PTC or follicular adenomas." (PMID 37833989, 2023). "Alternatively, several studies have indicated that annexin A5 is negatively correlated with tumorigenesis in diffuse large B-cell lymphoma and thyroid cancer." (PMID 35805203, 2022).
non-small cell lung carcinoma (10 papers, 2011 to 2025). A group of at least three distinct histological types of lung cancer, including non-small cell squamous cell carcinoma, adenocarcinoma, and large cell carcinoma. "However, the role of ANXA5 in non-small cell lung cancer, and especially in resistance to EGFR tyrosine kinase inhibitors, is poorly understood." (PMID 29784046, 2018).
colitis (9 papers, 2012 to 2025). Inflammation of the colon. "In trinitrobenzene sulfonic acid (TNBS)-induced colitis, PS inhibition by annexin A5 alleviated disease via reduced inflammatory cell infiltration due to inhibition of endothelial cell activation." (PMID 39956825, 2025). "The disease activity index (DAI) indicated the protective role of ANXA5 treatment in TNBS-induced colitis." (PMID 34131110, 2021). "Together, these results indicated that the PS-binding ability of ANXA5 was critical for the anti-inflammatory effect in TNBS-induced colitis." (PMID 34131110, 2021). "ANXA5 administration significantly reduced the inflammatory cell infiltration in TNBS-induced colitis, which was probably due to its inhibitory effect on leukocyte adhesion to endothelial cells." (PMID 34131110, 2021). "ANXA5 effectively alleviates TNBS-induced colitis by inhibiting inflammatory cell infiltration." (PMID 34131110, 2021). "Next, we examined the distribution of ANXA5-TagRFP in mice with colitis." (PMID 34131110, 2021). "PS exposure provides the basis for targeted delivery of ANXA5 in the treatment of colitis." (PMID 34131110, 2021). "Annexin A5 (ANXA5) with high affinity for PS has a good targeting to the colon and effectively alleviates experimental colitis." (PMID 34131110, 2021). "In contrast, ANXA5 mutant (A5m) lacking the PS-binding ability, has no accumulation in the colon and no therapeutic effects on colitis." (PMID 34131110, 2021).
acute myeloid leukemia (8 papers, 2013 to 2025). Acute myeloid leukemia (AML) is a group of neoplasms arising from precursor cells committed to the myeloid cell-line differentiation. "In marked contrast to these data, it has been reported that positive ANXA5 expression correlates with a better prognosis in adult acute myeloid leukemia (AML), and a tumor suppressor role has been described in gastric cancer cells through the repression of ERK pathway." (PMID 36247003, 2022).
endothelial dysfunction (8 papers, 2012 to 2025). In vascular diseases, endothelial dysfunction is a systemic pathological state of the endothelium (the inner lining of blood vessels) and can be broadly defined as an imbalance between vasodilating and vasoconstricting substances produced by (or acting on) the endothelium. "Systemic endothelial dysfunction in 40-week-old BALB/c mice was associated with a tendency of lower eNOS expression, tendency of lower level of phosphorylated eNOS at S633 in the aorta, and altered plasma levels of selected systemic endothelial dysfunction biomarkers sICAM-1, t-PA, Ang-1, ANXA5." (PMID 36504711, 2022).
lung adenocarcinoma (8 papers, 2015 to 2022). A carcinoma that arises from the lung and is characterized by the presence of malignant glandular epithelial cells. "According to the results from TCGA, the expression levels of ANXA5 in NSCLC tissues were significantly lower in lung squamous cell carcinoma (LUSC) and lung adenocarcinoma (LUAD) compared to matched normal samples, which is consistent with our proteomic result from LUSC and adjacent normal tissues." (PMID 27684953, 2016).
Hyperglycemia (7 papers, 2012 to 2022). An increased concentration of glucose in the blood. "Therefore, it is proposed that the hyperglycemia decreases sphingomyelin availability and thus ceramide production around lesion area, which in turn disrupts the association of ceramide with annexin A5." (PMID 35874544, 2022). "During hyperglycemia, ischemic preconditioning did not reduce annexin A5 targeting at all." (PMID 23051145, 2012).
ischemia (7 papers, 2009 to 2025). A hypoperfusion of the BLOOD through an organ or tissue caused by a PATHOLOGIC CONSTRICTION or obstruction of its BLOOD VESSELS, or an absence of BLOOD CIRCULATION. "In a second set of experiments, we showed that targeting of both 99mTc-ANXA5 and 99mTc-DA5 to the ischemic muscle was blocked by administering 450 μg of unlabelled monomer ANXA5 prior to ischemia and the injection of labelled substrate." (PMID 21918686, 2011).
myocardial ischemia (7 papers, 2014 to 2022). A disorder of cardiac function caused by insufficient blood flow to the muscle tissue of the heart. "In this study, we investigated the effect of AnxA5 on left ventricular (LV) function and remodeling three weeks after myocardial ischemia-reperfusion (MI-R) injury in hypercholesterolemic ApoE*3-Leiden mice." (PMID 29712962, 2018).
nasopharyngeal carcinoma (7 papers, 2011 to 2024). A carcinoma arising from the nasopharyngeal epithelium. "Also, in a nasopharyngeal carcinoma cell line, the up-regulation of ANXA5 was suggested as a possible cause of resistance for cis-diamminedichloroplatinum vincristine, carboplatin–taxotere, and 5-fluorouracil." (PMID 29443940, 2018). "Annexin A5 may also be used as a biomarker in the study of diseases, such as tumours and asthma, and may promote the occurrence and development of laryngeal cancer and nasopharyngeal carcinoma (Zhang, Meng & Jing, 2022)." (PMID 37753171, 2023).
Alzheimer disease (6 papers, 2013 to 2025). A progressive, neurodegenerative disease characterized by loss of function and death of nerve cells in several areas of the brain leading to loss of cognitive function such as memory and language. "Researchers from Japan assessed the association of plasmatic annexin A5 with Alzheimer's disease and with Dementia with Lewy Bodies, and they found annexin A5 is indeed a good markers of both conditions." (PMID 25374540, 2014). "For example, the characteristic of ANXA5 inhibits the binding between amyloid β and PS, resulting in the accumulation of neurotoxic amyloid β in the choroid plexus of Alzheimer’s disease patients, ultimately leading to cellular death." (PMID 40342928, 2025).
rheumatoid arthritis (6 papers, 2009 to 2024). A chronic, systemic autoimmune disorder characterized by inflammation in the synovial membranes and articular surfaces. "The inflammatory targets that mediate rheumatoid arthritis mainly include (TNF, PTPN11, IL6, etc.); the main targets that mediate RA oxidative stress are NOS3; the targets that mediate the destruction of extracellular matrix tissue in RA mainly include (MMP9, MMP2, ANXA5, etc.)." (PMID 38238321, 2024).
thrombophilia (6 papers, 2013 to 2024). A condition characterized by an abnormally high level of thrombi. "This study found that genotypes of seven thrombophilia genes, including MTHFR, SERPINE1, MTR, ANXA5, MTRR PROZ, and VEGFA, are associated with inherited thrombophilia risk for RPL-RIF." (PMID 39498089, 2024).
asthma (5 papers, 2010 to 2023). "Our results indicate that acupuncture downregulates the expression of proinflammatory proteins (e.g., S100A8, RAGE, and S100A11) and upregulates the expression of anti-inflammatory proteins (e.g., CC10, ANXA5, and sRAGE) in the lung tissues of rats with asthma onset." (PMID 23304218, 2012). "We also detected decreased expression of PRDX6 and increased expression of ANXA5 in the acupuncture-treated model; however, these two proteins did not exhibit altered expression in asthma onset in rats when compared with the controls." (PMID 23304218, 2012).
autoimmune disease (5 papers, 2013 to 2025). A disorder resulting from loss of function or tissue destruction of an organ or multiple organs, arising from humoral or cellular immune responses of the individual to their own tissue constituents. "Additionally, the interaction of vorinostat with ANXA5, a protein that regulates inflammation and apoptosis, further supports its potential to modulate immune cell death and survival, crucial in autoimmune diseases." (PMID 40826785, 2025).
cholangiocarcinoma (5 papers, 2021 to 2025). A carcinoma that arises from the intrahepatic biliary tree (intrahepatic cholangiocarcinoma) or from the junction, or adjacent to the junction, of the right and left hepatic ducts (hilar cholangiocarcinoma). "Previous studies have demonstrated that inhibition of ANXA5 reduced the proliferation of murine hepatocarcinoma Hca-P cells with about a 25% lymph node metastasis rate, human cholangiocarcinoma cells, and pre-osteoblastic cells." (PMID 40438404, 2025).
coronary artery disease (5 papers, 2009 to 2024). "Quantitative measurements of CD31/Annexin A5-positive EVs were also taken in patients with stable coronary artery disease." (PMID 37293281, 2023).
heart failure (5 papers, 2009 to 2024). Inability of the heart to pump blood at an adequate rate to meet tissue metabolic requirements. "Interestingly, in heart failure patients responding to cardiac resynchronization therapy, reverse LV remodeling is associated with reduction in plasma AnxA5." (PMID 23284897, 2012). "AnxA5 levels were significantly increased in patients with heart failure compared with healthy subjects." (PMID 38474114, 2024). "In hypertensive patients with heart failure, release of AnxA5 from the heart has been suggested by the existence of a coronary sinus-peripheral venous AnxA5 concentration gradient." (PMID 23284897, 2012).
bladder tumor (4 papers, 2019 to 2025). "Our study confirmed the heightened ANXA5 expression in bladder tumours compared to normal tissues, and we observed that disrupting ANXA5 expression inhibited BLCA cell migration." (PMID 39400959, 2024).
endotoxemia (4 papers, 2020 to 2023). "Animal survival in endotoxemia was improved, showing significant improvements not only when annexin A5 was injected immediately after LPS injection, but also with delayed annexin A5 treatment 4 h after LPS injection." (PMID 34566657, 2021). "Although annexin A5 is extensively used as an indicator of early apoptosis, it was demonstrated that annexin A5 exerts protective functions including inhibition of proinflammatory response and improvement of cardiac function and survival during endotoxemia in mice." (PMID 32523019, 2020).
fibrosarcoma (4 papers, 2014 to 2024). A malignant mesenchymal fibroblastic neoplasm affecting the soft tissue and bone. "It has been reported that Anxa5 up-regulation correlates with the inflammation-associated carcinogenesis of fibrosarcoma." (PMID 25287937, 2014). "Three proteins: ANXA5, ANXA3, and MNS1 were identified to be significantly (p ≤ 0.05) differentially expressed in doxorubicin-resistant fibrosarcomas in comparison to doxorubicin-sensitive ones." (PMID 29443940, 2018).
Hypercholesterolemia (4 papers, 2017 to 2022). An increased concentration of cholesterol in the blood. "These mice mimic the clinical situation of most MI patients regarding hypercholesterolemia, and thereby adding more value to the found cardioprotective effect of AnxA5." (PMID 29712962, 2018).
Lung Fibrosis (4 papers, 2023 to 2025). "In conclusion, our results indicate that CA alleviated lung fibrosis by targeting the ANXA5‐PKCθ‐NF‐κB signaling axis in BLM‐induced mouse models." (PMID 41476649, 2025). "Preliminary, unpublished data from a bleomycin-induced pulmonary fibrosis model further support the anti-fibrotic efficacy of AnxA5 across multiple tissue types." (PMID 40871009, 2025). "Moreover, CA alleviated lung fibrosis and decreased inflammation levels by targeting ANXA5 in bleomycin‐induced mouse models." (PMID 41476649, 2025). "It has also been shown that Annexin A5 may affect the occurrence and development of pathological phenomena, such as tumour diseases, pulmonary fibrosis and lung injury." (PMID 37753171, 2023).
osteoarthritis (4 papers, 2022 to 2025). A noninflammatory degenerative joint disease occurring chiefly in older persons, characterized by degeneration of the articular cartilage, hypertrophy of bone at the margins and changes in the synovial membrane. "The expression and distribution of ANXA5 could serve as a histological marker for metabolic alterations and changes in cell phenotype associated with osteoarthritis." (PMID 40342928, 2025). "Research by Mollenhauer has demonstrated that ANXA5 is significantly upregulated in the cartilage of patients with osteoarthritis." (PMID 40342928, 2025). "In vivo, studies revealed that intra-articular administration of AnxA5 ameliorated pain symptoms in a monosodium iodoacetate-induced osteoarthritis rat model." (PMID 38904008, 2024). "Annexin A5 (ANXA5) played an important role in matrix vesicle-mediated biomineralization during endochondral ossification and osteoarthritis." (PMID 35496280, 2022).